RN7SL774P (RNA, 7SL, cytoplasmic 774, pseudogene)
Gene: Miscellaneous RNA gene on chromosome 17 (4,364,164 to 4,364,453, reverse strand). Ensembl gene ENSG00000263882.
Homologues: Orthologues: chimpanzee Metazoa_SRP (83% identical), chimpanzee Metazoa_SRP (82% identical), macaque Metazoa_SRP (76% identical). Paralogues in human: RN7SL134P (86% identical), Metazoa_SRP (86% identical), RN7SL96P (85% identical), RN7SL474P (83% identical), RN7SL811P (83% identical), RN7SL784P (83% identical), Metazoa_SRP (82% identical), RN7SL154P (82% identical), RN7SL596P (82% identical), RN7SL391P (81% identical), Metazoa_SRP (81% identical), Metazoa_SRP (80% identical), and 710 more.